GRK4 (G protein-coupled receptor kinase 4)
Description:
Specifically phosphorylates the activated forms of G protein-coupled receptors. GRK4-alpha can phosphorylate rhodopsin and its activity is inhibited by calmodulin; the other three isoforms do not phosphorylate rhodopsin and do not interact with calmodulin. GRK4-alpha and GRK4-gamma phosphorylate DRD3. Phosphorylates ADRB2.
Synonyms: GPRK2L; GPRK4; GRK4a; IT11
Tractability: Small molecule: a structure with a bound ligand is known; a high-quality ligand is known; it belongs to a druggable protein family. Antibody: its Gene Ontology location is reachable by antibodies, with high confidence. PROTAC: ubiquitination databases record sites on it; a small molecule that binds it is known.
Target class: AGC protein kinase GRK family; Kinase; AGC protein kinase group; AGC protein kinase GRK subfamily; Enzyme; Protein Kinase
Safety:
Unwanted effects reported when the protein is acted on. In parentheses: how it was acted on, where the effect was seen, and who reports it.
adverse cardiovascular outcomes (source: ClinPGx)
Gene: Protein-coding gene on chromosome 4 (2,963,571 to 3,040,760, forward strand). Ensembl gene ENSG00000125388.
Subcellular location: Cytoplasm; Cytoplasm, cell cortex
Subcellular location (Human Protein Atlas): Cytosol; Plasma membrane; Calyx
Pathways (Reactome):
Sensory Perception: Inactivation, recovery and regulation of the phototransduction cascade
Gene Ontology:
Molecular function: G protein-coupled receptor kinase activity; protein binding; protein serine/threonine kinase activity; protein kinase activity; rhodopsin kinase activity; ATP binding
Biological process: desensitization of G protein-coupled receptor signaling pathway; receptor internalization; regulation of G protein-coupled receptor signaling pathway; regulation of opsin-mediated signaling pathway; regulation of signal transduction; signal transduction
Cellular component: cytosol; cytoplasm; photoreceptor disc membrane; cell cortex
Genetic constraint (gnomAD): Loss-of-function variants: 44 observed, 44.83 expected, observed/expected ratio (o/e) 0.98, 90% interval 0.77 to 1.26. The upper end of that interval is the gene's LOEUF score, 1.26, which puts it in group 5 of 6, group 1 being the genes least tolerant of losing a copy. Missense variants: 491 observed, 499.95 expected, observed/expected ratio (o/e) 0.98, 90% interval 0.91 to 1.06. Synonymous variants: 180 observed, 183.45 expected, observed/expected ratio (o/e) 0.98, 90% interval 0.87 to 1.11.
Homologues: Orthologues: chimpanzee GRK4 (99% identical), rabbit GRK4 (81% identical), dog GRK4 (79% identical), pig GRK4 (77% identical), mouse Grk4 (75% identical), rat Grk4 (74% identical), zebrafish grk4 (74% identical), tropical clawed frog grk4 (69% identical), Drosophila melanogaster Gprk2 (58% identical), Caenorhabditis elegans grk-1 (55% identical). Paralogues in human: GRK5 (66% identical), GRK6 (65% identical), GRK1 (44% identical), GRK7 (43% identical), GRK3 (36% identical), GRK2 (35% identical), RSKR (17% identical).
Diseases named in the same sentence as GRK4 in open-access papers:
GRK4 is named in the same sentence as 30 diseases in open-access papers, as found by Europe PMC text mining. Sharing a sentence is not in itself a finding about the gene and the disease. The quoted sentences say what the papers report.
Hypertension (26 papers, 2012 to 2025). The presence of chronic increased pressure in the systemic arterial system. "In this context, GRK4 variants contribute to hypertension through disruption of the signaling of dopamine D1 receptor and angiotensin type 1 receptor (AT1R)." (PMID 39743506, 2025). "The etiology of essential hypertension is best understood in the context of the way in which pathogenic GRK4 variants interact with other systems involved in blood pressure regulation." (PMID 39743506, 2025). "It should be noted that recent studies reported that some new GRK4 variants are associated with hypertension (GRK4 rs1644731), both hypertension and diabetes (GRK4 rs1557213), or cardiovascular disease risk and diabetes (GRK4 rs60314379)." (PMID 38961282, 2024). "We presume that the polymorphisms alter the structure of GRK4, that modulate its kinase activity, and affect substrate-regulated biological responses that subsequently cause hypertension." (PMID 38961282, 2024). "Several GRK4 gene variants, e.g., R65L, A142V, and A486V, are positively associated with essential hypertension in several ethnic populations." (PMID 38961282, 2024). "The GRK4 locus on human chromosome 4p16.3 is associated with essential hypertension and salt sensitivity." (PMID 38961282, 2024). "GRK4 has been demonstrated to be associated with an increased risk of hypertension, indicating hypertension as an important factor in breast cancer." (PMID 35326596, 2022). "For example, CAMK4 rs10491334 is associated with hypertension in Uyghur population; whereas GRK4 rs180105 in East Asians and Europeans; and GRK4 rs2960306 in Europeans." (PMID 34297769, 2021). "Six non-synonymous mutations related to hypertension were identified, including GRK4 rs1644731 and RDH8 rs1801058, Mutations are predicted to affect 3D conformation, force field, transmembrane domain and RNA secondary structure of corresponding genes." (PMID 34297769, 2021). "Studies indicate that GRK4 gene polymorphisms are associated with susceptibility to hypertension in the European population and Caucasians." (PMID 32714484, 2020). "By contrast, for low-renin hypertension, a two-locus model that includes the GRK4 A142V variant and cytochrome P450 11B2 (CYP11B2) C-344 T was 77.8% predictive." (PMID 30621627, 2019). "The GRK4 gene variants that are associated with hypertension increase renal proximal tubule AT1R expression and activity." (PMID 27390269, 2016). "Current evidence shows that common variants of GRK4 are associated with human essential hypertension and predict the blood pressure response to antihypertensive medicines." (PMID 27390269, 2016). "A number of studies have shown the genetic association of the 3 GRK4 SNPs with human essential hypertension in several ethnic groups." (PMID 27390269, 2016). "In conclusion, there is considerable evidence that GRK4 variants are linked to impaired Na excretion, hypertension in animal models and humans, therapeutic response to dietary Na restriction and response to antihypertensive drugs." (PMID 25775155, 2015). "There is now mounting evidence that GRK4 variants are linked to impaired Na excretion, hypertension in animal models and humans, therapeutic response to dietary Na restriction and response to antihypertensive drugs." (PMID 25775155, 2015). "In humans, GRK4 polymorphisms were shown to be associated with essential hypertension in Australia, BP regulation in young adults, low renin hypertension in Japan and impaired stress-induced Na excretion in normotensive black men." (PMID 25775155, 2015). "Dopamine D1A receptor function is impaired in both of obesity-induced insulin resistance and GRK4 variants, contributing to salt-sensitive hypertension and essential hypertension." (PMID 25768006, 2015). "In an Australian study, involving 168 unrelated white subjects/patients and 312 normotensive controls, GRK4 polymorphisms were associated with essential hypertension." (PMID 25775155, 2015).
Hypertension (continued). "GRK4 variants have been shown to be associated with hypertension and blood pressure traits in different populations including Han Chinese." (PMID 24658007, 2014). "Variants of GRK4 have been implicated in the development of hypertension." (PMID 39743506, 2025). "In addition to being the source of hypertension, persistent activation of the GRK4 single nucleotide polymorphism genotype (A142 V or R65L, A486V) was often seen in breast cancer cell lines." (PMID 38638965, 2024). "GRK4 has been linked to the etiopathogenesis of essential hypertension." (PMID 35769816, 2022). "Among them, 5 candidates interacting with GRK4 were associated with hypertension." (PMID 34297769, 2021). "Therefore, this study mainly studied how the two genes, RDH8 rs1644731 and GRK4 rs1801058, and their mutation sites play a role in the pathogenesis of hypertension in Han people in Xinjiang." (PMID 34297769, 2021). "G protein-coupled receptor kinases (GRKs) participate in the desensitization of G protein-coupled receptors, including D1 receptors, in the proximal renal tubules; variants in GRK4 (4p16.3) were shown to improperly excrete sodium in rodents and humans with hypertension." (PMID 30832344, 2019). "Studies have shown that increased GRK4 activity causes impaired renal D1R function in hypertension." (PMID 27390269, 2016). "Of the four GRK4 variants reported by Jones and colleagues, the GRK4 rs2960306 (c.194G>T, p.Arg65Leu), rs1024323 (c.425C>T, p.Ala142Val), and rs1801058 (c.1457T>C, p.Val486Ala) were previously reported to be associated with altered activity of the protein and hypertension." (PMID 38633331, 2023). "The polymorphisms in the GRK4 gene are associated with the etiology of arterial hypertension by regulating phosphorylation and the function of dopamine receptors in proximal renal tubule cells which may lead to a decrease in sodium elimination and a consequent increase in blood pressure." (PMID 32714484, 2020). "Additionally, the number of GRK4 variants was inversely related to salt excretion, suggesting that GRK4 is an important gene in the regulation of the hyporeninemic hypoaldosteronism phenotype in African Americans with hypertension." (PMID 30832344, 2019). "In South Africa, GRK4 polymorphisms are more common in people of African descent, associated with impaired Na excretion in normotensive African people, and predict blood pressure response to Na restriction in African patients with mild to moderate essential hypertension." (PMID 25775155, 2015). "In South Africa, GRK4 polymorphisms are more common in people of African descent, are associated with impaired Na excretion in normotensive people, and predict blood pressure response to Na restriction in African patients with mild to moderate essential hypertension." (PMID 25775155, 2015). "Genetic studies in humans also display that GRK4 is correlated with hypertension and blood pressure response to antihypertensive medicines." (PMID 40763158, 2025). "GRK4 variants associated with inappropriate desensitization of the dopamine D1 receptor in renal proximal tubules in hypertension may result in the decreased ability of the kidney to eliminate a sodium chloride load, a key risk factor in the development of hypertension." (PMID 39743506, 2025). "The role of GRK4 in hypertension is further confirmed by studies involving renal Grk4 depletion, which efficiently reduces GRK4 expression and lowers blood pressure in SHRs, accompanied with increased urine volume and sodium excretion." (PMID 38961282, 2024). "Currently, studies directly investigating GRK4 in COPD are limited; however, there is substantial evidence linking GRK4 genetic variation to hypertension, where it plays a critical role in regulating receptor expression and function related to blood pressure." (PMID 39558015, 2024). "GRK4-mediated regulation of D1R expression or activity has been confirmed in several animal models of hypertension." (PMID 38961282, 2024).
Hypertension (continued). "The role of GRK4 in the regulation of blood pressure is confirmed in several animal models of hypertension." (PMID 38961282, 2024). "In hypertension, the adiponectin stimulatory effect on sodium excretion is impaired; this is credited to the increased expression and activity of G protein-coupled receptor kinase 4 (GRK4)." (PMID 35890325, 2022). "It was observed that pharmacogenetic variants, rs1024323 and rs1801058 (F110V, A142V, Y292A, V486A, and F454A) evoked a phenotypic effect (Hypertension, Nephrosclerosis and Kidney issues) on the interaction between GRK4 gene and Metoprolol drug." (PMID 35865963, 2022). "GRK4 plays an important role in the phosphorylation and regulation of dopamine D1 receptors, and when overexpressed induces hypertension; although, GRK4 is mainly expressed in the testis, cerebellum, and kidneys." (PMID 35430346, 2022). "Based on protein interaction network and pathway enrichment, GRK4 is predicted to participate in hypertension by acting on dopaminergic synapse, together with interacting components." (PMID 34297769, 2021). "In summary, GRK4 and RDH8 are genetic risk factors for essential hypertension in Han Chinese in Xinjiang." (PMID 34297769, 2021). "Variants of the AT1 receptor of angiotensin II (AGTR1) and other genetic polymorphisms such as the G protein-coupled receptor kinase 4 (GRK4) and solute carrier family 12 member 3, SLC12A3, have been related to arterial hypertension and atherosclerosis." (PMID 32714484, 2020). "Basal GRK4 expression in the renal cortex is much higher in SHRs than in WKY rats, whereas cardiac GRK4 expression is similar in the 2 rat strains, indicating that the increased GRK4 expression in hypertension has organ specificity." (PMID 27390269, 2016). "In this current study, we investigated the potential role of GRK4 in the modulation of Mas receptor and demonstrated that aberrant regulation of GRK4 on Mas receptor may be involved in the pathogenesis of hypertension." (PMID 40763158, 2025). "These suggest that GRK4 contributes to increased renal Mas receptor phosphorylation and dysfunction in hypertension, indicating that targeting GRK4 may be a viable therapeutic approach for hypertension." (PMID 40763158, 2025). "Especially, our previous studies have reported that constitutively active GRK4 variants (e.g., A142V) leads to the dysfunction of renal AT1R and AT2R, the two main effectors of Ang II, which is involved in the pathogenesis of hypertension." (PMID 40763158, 2025). "In addition, GRK4 expression and activity in the kidney and artery are increased in other animal models of hypertension." (PMID 38961282, 2024). "Given the interplay between COPD and hypertension, it is plausible that GRK4 may play a cross-functional role in the pathogenesis of both conditions via shared pathophysiological pathways." (PMID 39558015, 2024). "It was revealed that GRK4 and PPARs are significant regulators of hypertension and HCC [6,15,]." (PMID 38638965, 2024). "Most studies have focused on GRK4's role in hypertension management, with few demonstrating GRK4's role in neuron function transmission via γ-aminobutyric acid desensitization and the maintenance of endocrine function via luteinizing hormone/follicle-stimulating hormone." (PMID 38638965, 2024). "Consequently, GRK4 was discovered to be an oncogene in breast cancer and a co-regulator of hypertension." (PMID 38638965, 2024). "Recent studies have shown that GRK4 expression is inherently upregulated in the kidneys and arteries of patients with essential hypertension and is significantly influenced by environmental factors such as cold stress, particulate matter (PM) exposure, and infection." (PMID 39558015, 2024). "Therefore, in this study, we focused on how RDH8 rs1644731 and GRK4 rs1801058 correlate with hypertension in Han people in Xinjiang." (PMID 34297769, 2021).
Hypertension (continued). "Therefore, the selection of better approaches to suppress renal GRK4 expression is an important issue for the regulation of sodium excretion and BP in hypertension." (PMID 27792639, 2016). "Increased GRK4 activity leads to decreased dopamine signaling and increased AngII receptor expression and function, both of which increase sodium retention and blood volume which ultimately leads to hypertension." (PMID 24658007, 2014). "However, it remains unclear whether renal Mas receptor, another important component of RAS, is also regulated by GRK4 and its role in the pathogenesis of hypertension." (PMID 40763158, 2025). "However, it is still unknown whether renal Mas receptor is also regulated by GRK4 and its role in the pathogenesis of hypertension." (PMID 40763158, 2025). "However, it remains unknown whether renal Mas receptor is regulated by GRK4 and its role in the pathogenesis of hypertension." (PMID 40763158, 2025). "In addition, an earlier meta-analysis showed that GRK4 rs1024323 is associated with hypertension in Caucasians, but not in East Asians and Africans." (PMID 38961282, 2024). "Our results indicate that UTMD‐targeted GRK4 siRNA delivery to the kidney effectively reduces D1R phosphorylation by inhibiting renal GRK4 expression, improving D1R‐mediated natriuresis and diuresis, and lowering BP, which may provide a promising novel strategy for gene therapy for hypertension." (PMID 27792639, 2016). "Thus, GRKs such as GRK4 may be therapeutic targets in hypertension." (PMID 39743506, 2025). "Thus, GRK4 and RDH8 may serve as susceptibility genes for hypertension." (PMID 34297769, 2021). "In order to explore potential effects of GRK4 and RDH8 on hypertension pathogenesis, a PPI network was constructed." (PMID 34297769, 2021). "Since the discovery of a linkage between GRKs and cardiovascular disease including hypertension and heart failure, GRKs—especially GRK2 and GRK4—have been considered pharmaceutical targets for the treatment of cardiovascular disease." (PMID 27390269, 2016). "GRK4 and ADRB2 may play synergistic roles in hypertension through dysregulating SNS." (PMID 34297769, 2021). "GRK4 and RDH8 may interact with these proteins involved in hypertension." (PMID 34297769, 2021).
breast carcinoma (3 papers, 2022 to 2024). "Initially, more than one GRK4 isoform (GRK4β/δ, GRK4α/β/δ, and GRK4β/γ/δ) were detected in tumor tissues obtained from the same patient with breast cancer." (PMID 38638965, 2024). "cMyc a protooncogene responsible for cell proliferation in various cancers, transcriptionally regulates GRK4 protein that was reported to be overexpressed in breast cancer tissues." (PMID 35326596, 2022). "GRK4 stimulated the growth of breast cancer cells (MCF-7) via the MAPK signaling pathway." (PMID 38638965, 2024). "Importantly, several papers have reported the role of GRK4 in the pathogenesis of breast cancer." (PMID 38638965, 2024). "In breast cancer, the prognostic significance of GRK6 or its role in modulating cancer metastasis remains largely unknown even though GRK2 and GRK4, not GRK3, upregulation have been found to promote tumorigenesis, migration/invasion and metastasis in breast cancer cells." (PMID 39741338, 2024).
hepatocellular carcinoma (3 papers, 2022 to 2024). A malignant tumor that arises from hepatocytes. "The current study used proteomics techniques to investigate the mechanism of GRK4 regulation of hepatoma cells." (PMID 38638965, 2024). "The present study was aimed at assessing the prognostic value of GRK4 in hepatocellular carcinoma (HCC)." (PMID 35769816, 2022).
thyroid nodule (3 papers, 2016 to 2024). A small circumscribed mass in the THYROID GLAND that can be of neoplastic growth or non-neoplastic abnormality. "The influence of GRK4 was confirmed by the existence of hyperfunction thyroid nodules." (PMID 38638965, 2024). "GRK4 was overexpressed in hyperfunctioning thyroid nodules (HTNs) compared with their adjacent tissues but failed to induce thyroid-stimulating hormone receptor (TSHR) desensitization, which may cause HTN." (PMID 35769816, 2022).
myocardial infarction (2 papers, 2022 to 2024). Gross necrosis of the myocardium, as a result of interruption of the blood supply to the area, as in coronary thrombosis. "The GRK4 variant A486V has been shown to increase the impairment of cardiac function after myocardial infarction." (PMID 38961282, 2024). "We also reported its expression in the artery and heart, and found that renal and cardiac GRK4 levels are elevated by kidney ischemia-reperfusion injury and myocardial infarction, respectively." (PMID 38961282, 2024).